PINK1 (PTEN induced kinase 1)
Diseases named in the same sentence as PINK1 in open-access papers (continued):
Sharing a sentence is not in itself a finding about the gene and the disease.
Onset (38 papers, 2005 to 2026). The age group in which disease manifestations appear. "Among these, mutations in the PTEN-induced putative kinase 1 (PINK1) gene are linked to autosomal recessive early-onset PD." (PMID 41602154, 2026). "Mutations in PTEN-induced putative kinase 1 (PINK1) are known to cause autosomal recessive early-onset PD." (PMID 41022756, 2025). "PTEN-induced putative kinase 1 (PINK1) mutations are associated with autosomal recessive early-onset PD." (PMID 37694119, 2023). "The loss-of-function mutations of PTEN-induced kinase 1 (PINK1) or Parkin are responsible for autosomal recessive early-onset PD." (PMID 36829773, 2023). "One of the genes which has been linked to the onset of juvenile/early onset Parkinson’s disease (PD) is PINK1." (PMID 34074800, 2021). "PINK1 (PTEN-induced putative kinase 1) gene mutations, although rare, are the second most common cause of recessively inherited early-onset PD, after Parkin gene mutations." (PMID 34831247, 2021). "Evidence of this is that PINK1 and Parkin, both involved in mitochondrial dynamics and quality control, are the main cause of autosomal recessive (AR) early-onset PD." (PMID 34831247, 2021). "PARK2, PARK7, and PINK1 are known to cause early-onset PD with a recessive inheritance mode, while SNCA and LRRK2 are known to cause dominantly inherited PD." (PMID 30917570, 2019). "Mutations in PRKN and PTEN-Induced Putative Kinase 1 (PINK1) are well-established causes of autosomal recessive early-onset PD." (PMID 31344817, 2019). "As demonstrated in the application scenario, mutations in the PINK1 gene is well known for their causal association to familial early onset PD but their mechanistic model reveals their potential involvement in the etiology of sporadic late onset PD as well." (PMID 26395080, 2015). "Another PD-related protein, PINK1, is encoded by the PINK1/PARK6 gene, mutations in which cause autosomal recessive early-onset PD; this protein has been shown to bind to HDAC3 and increase its histone deacetylase activity via phosphorylation in neuronal cells." (PMID 33003340, 2020). "Human genetic studies revealed that homozygous mutations in mitochondrial kinase PINK1 cause autosomal recessive, early-onset PD, whereas heterozygous mutations in PINK1 increase the risk for developing late-onset PD, highlighting the importance of knowing the sites and mechanisms of PINK1 action." (PMID 26740872, 2016). "A mitochondrion-associated kinase protein, phosphatase, and tensin homolog (PTEN)-induced kinase 1 (PINK1), was identified in patients with early-onset PD." (PMID 41351658, 2025). "Mutations in several genes, including PTEN-induced putative kinase 1 (PINK1) and the parkin gene parkin RBR E3 ubiquitin protein ligase (PARK2), cause autosomal recessive early onset PD in association with the accumulation of misfolded proteins." (PMID 39403921, 2024). "Mutations of the genes coding for PINK1 (PARK6) and Parkin (PARK2) are the most frequent causes of autosomal recessive early-onset PD." (PMID 37951933, 2023). "LOF mutations in the serine/threonine kinase PINK1 (PARK6) and E3 ubiquitin ligase Parkin (PARK2) represent the most common cause of autosomal recessive familial early-onset PD." (PMID 35801175, 2022). "Mutations in the PINK1 (PARK6) gene, a mitochondrial-targeted serine-threonine kinase, cause autosomal recessive early-onset PD." (PMID 36139853, 2022). "Supporting this notion are mutations in an additional gene, PARK6 (encoding PTEN-induced kinase 1; PINK1), that also causes autosomal recessive early-onset PD that is often phenotypically similar to cases caused by PARK2." (PMID 34897410, 2021). "PARK6 defects and the resultant deficiency of PINK1 lead to mitochondrial dysfunctions and the development of autosomal recessive and early-onset PD." (PMID 34239490, 2021).
Onset (continued). "To this aim, we used a well-characterized mouse model of autosomal recessive early-onset Parkinson’s disease (PD), the phosphatase and tensin homolog (PTEN) induced kinase 1 (PINK1) knockout mouse model." (PMID 31336695, 2019). "In early-onset PD, mutations in six specific genes (SNCA, PRKN, PINK1, DJ1, LRRK2, and GBA) have been reported to account for 16% of cases; these specific mutations are not directly accounted for in our estimate, which is based on a polygenic model." (PMID 21738487, 2011). "Additionally, single heterozygous mutations in PRKN and PINK1 genes are considered minor genetic risk factors for developing PD and single heterozygous substitutions in PRKN gene have been described in sporadic, late-onset PD." (PMID 31737044, 2019). "Similarly, in case of PD, scientists have focused on the function of Parkin and PTEN-induced putative kinase 1 (PINK1), two proteins mutated in familial, early-onset Parkinson's disease and recommended drugs for therapies that boost mitophagy or stimulate activity of Parkin/PINK1." (PMID 27721743, 2016).
Cognitive impairment (35 papers, 2016 to 2026). Abnormal cognition is characterized by deficits in thinking, reasoning, or remembering. "Except for GBA-PINK1 is the PD-associated gene showing the highest rate of cognitive impairment, mainly concerning attention and executive functions, while the prevalence of depression is comparable between PINK1 patients and idiopathic PD." (PMID 34831247, 2021). "This is consistent with previous studies showing that PRKN and PINK1 mutations are generally associated with slower disease progression and less cognitive impairment." (PMID 31324919, 2019). "In the present study, we report a novel homozygous missense mutation in exon 8 of PINK1 gene in a Moroccan PD patient with a rapid progression and a mild cognitive impairment." (PMID 27413743, 2016). "Interestingly, significant cognitive impairments are frequently observed among human PINK1 mutation carriers, and PINK1 plays an important role in promoting dendritic branching, synaptic spine density in vitro and in vivo, and spine maturation." (PMID 41277110, 2026). "Furthermore, in diabetes-associated cognitive impairment models, UA enhances PINK1/Parkin-dependent mitophagy, improving neuronal mitochondrial function and ameliorating cognitive deficits." (PMID 40722629, 2025). "In this study, PINK1 overexpression rescued neuron loss and synaptic damage, and ameliorated cognitive impairments by promoting the degradation of accumulated tau in the autophagy pathway, reducing tau accumulation in mitochondria and alleviating mitochondrial disorders." (PMID 35059394, 2021). "Therefore, we aimed to investigate the underlying mechanisms by which PINK1 ameliorated cognitive deficits in hTau mice." (PMID 35059394, 2021). "An earlier review that used MDSGene data and included a total of 1127 patients with causative Parkin (n = 958), PINK1 (n = 139) or DJ1 (n = 30) mutations suggests that cognitive impairment was present in only a small percentage of subjects with PINK1 associated PD." (PMID 34068064, 2021). "Here, using a mouse model of tauopathy injected with AAV2-full-length human TAU into the hippocampus, we showed that upregulation of PINK1 significantly alleviated the deposition of pathological tau, neuron loss, synaptic damage, and cognitive impairments in mice." (PMID 35059394, 2021). "However, we did find that PRKN and PINK1 mutation carriers have distinctive clinical features compared to young-onset non-carriers, with more postural symptoms at diagnosis and less cognitive impairment, after adjusting for age and disease duration." (PMID 31324919, 2019). "Similarly, recessive forms of familial PD, including Parkin-PD and PINK1-PD, are generally characterized by a lower frequency of cognitive impairment, while GBA gene mutations, another risk factors for PD, have shown an increased probability of developing dementia." (PMID 39519043, 2024). "Nevertheless, in Drosophila, very complex PD-like phenotypes and behaviors can be induced by mutations, e.g. in Pink1, including reduced life expectancy, decreasing motor skills, sleep fragmentation, olfactory dysfunctions, cognitive impairments and DA cell loss." (PMID 34125184, 2021). "Our findings have shown that the p.L539F is a novel mutation located in the C terminal sequence of the PINK1 protein that could be pathogenic and responsible for a clinical phenotype resembling idiopathic Parkinson's disease with rapid progression and early cognitive impairment." (PMID 27413743, 2016). "PINK1 PD cases are reported to have only MCI, and a systematic review of genetic autosomal recessive PD patients reported significant cognitive deficits in only 14% of PINK1-PD patients." (PMID 40722695, 2025). "Dexmedetomidine has been shown to reduce postoperative cognitive impairment in aged rats by promoting PINK1-mediated mitophagy and suppressing caspase-1/GSDMD-induced pyroptosis in hippocampal neurons." (PMID 39416788, 2024).
Cognitive impairment (continued). "Overexpression of PINK1 has been shown to alleviate cognitive impairment and reduce caspase-3/GSDME-dependent pyroptosis." (PMID 39416788, 2024). "Berberine mitigates cognitive impairment and Alzheimer’s-like pathology induced by D-ribose via promoting mitophagy, through which berberine inhibits PINK1 promoter methylation and promotes its expression." (PMID 36982968, 2023). "Taken together, these findings support the idea that TNFAIP1 silencing mitigates postoperative cognitive impairment, intensifies PINK1/Parkin-mediated mitophagy and restrains caspase-3/GSDME-mediated pyroptosis by stimulating SNAP25 protein expression." (PMID 38102610, 2023). "BBR ameliorates Alzheimer’s pathology and cognitive impairment of APP/PS1 mice induced by D-ribose through inhibiting PINK1 promoter methylation." (PMID 36982968, 2023). "Functional investigations further revealed that neuron-specific inhibition of TNFAIP1 alleviated postoperative cognitive disorders by intensifying PINK1/Parkin-dependent mitophagy and suppressing caspase-3/GSDME-dependent pyroptosis." (PMID 38102610, 2023). "Our previous research demonstrated that SNAP25 mitigated surgery-induced cognitive impairment by enhancing PTEN-induced kinase 1 (PINK1)/Parkin-dependent mitophagy as well as repressing caspase-3/gasdermin E (GSDME)-dependent pyroptosis." (PMID 38102610, 2023). "Recessive forms of familial PD, including Parkin-PD and PINK1-PD, are generally characterized by a lower frequency of cognitive impairment." (PMID 35003622, 2021). "Cognitive impairment is higher in GBA- and SNCA-associated PD, lower in Parkin- and PINK1-PD, and possibly milder in LRRK2-PD." (PMID 35003622, 2021). "Researchers showed that the increasing expression of PINK1 lessened Aβ plaques accumulation and rescued cognitive impairments in AD mice." (PMID 35059394, 2021). "Bacillus subtilis effectively preserves cognitive function through activation of PINK1/PTEN-dependent mitophagy and suppression of neuroinflammation, highlighting its potential as a therapeutic candidate for cognitive impairments associated with gut-brain axis dysfunction." (PMID 41892682, 2026). "Improving mitochondrial dysfunction can improve cognitive deficits through the PINK1 pathway." (PMID 41041049, 2025). "Importantly, berberine reversed D-ribose-induced cognitive impairment by demethylating the PINK1 promoter, restoring mitophagy via the PINK1–Parkin pathway." (PMID 40927759, 2025). "Indeed, cognitive impairment is higher in GBA- and SNCA-associated PD, lower in Parkin- and PINK1-PD, and possibly milder in LRRK2-PD." (PMID 39519043, 2024). "LncRNA nuclear enriched abundant transcript 1 (NEAT1) interacts with NEDD4L and promote PTEN-induced putative kinase 1 (PINK1)’s degradation, thereby the interaction between them is assumed to be responsible for mitochondria dysfunction and cognitive impairment." (PMID 38368488, 2024). "Furthermore, this study also documented that the induction of mitophagy and reversal of cognitive impairment involved the PTEN-induced kinase-1 (PINK-1) and parkin-dependent pathways." (PMID 36680084, 2022). "In multiple AD mouse models with Aβ and Tau pathology, the enhancement of the ALP expression by exogenous TFEB has been demonstrated to significantly reduce Aβ and Tau pathological changes, improve cognitive impairment, upregulate PINK1, and enhance autophagy/mitophagy." (PMID 35983247, 2022). "CQ also reversed the PINK1-induced improvements on cognitive impairment." (PMID 35059394, 2021). "Compounds such as urolithin A, actinonin, and spermidine activate PINK1/parkin - and NIX-dependent mitophagy, leading to attenuation of AD-related pathology, improved mitochondrial function, and ameliorated cognitive deficits." (PMID 40943612, 2025).
Cognitive impairment (continued). "Melatonin can reduce the levels of mitophagy proteins PINK1 and Parkin, decrease the colocalization of Tom20 and LC3, alleviate neuronal hypoxia after stroke, and improve post-stroke cognitive impairment (PSCI)." (PMID 39416788, 2024). "The heterozygous PINK1 deletion of exon 1 carrier (PD156) had appropriate features as previously reported, especially the depression mood and cognitive impairment (MoCA score: 23 points)." (PMID 36879366, 2023). "Additionally, PARK6-associated PD patients have also shown PINK1 deficiency and its impact on increased generation of pro-inflammatory cytokines and chemokines (e.g., IFNβ1, IL-6, IL-12, IL-13, CCL2, CCL4, and CXCL1), loss of NCs, and the development of cognitive defects." (PMID 34239490, 2021). "The heterozygous PINK1 deletion of exon 1 (PD156) was found in a recently diagnosed 48‐year‐old male with depressed mood; MDS‐UPDRS score 7‐20‐68‐6 each part, respectively, and cognitive impairment (MoCA of 23)." (PMID 36879366, 2023).
lung carcinoma (32 papers, 2015 to 2026). "In lung carcinoma tissue, the expression of PINK1 was raised, which was associated with a poor prognosis." (PMID 39443755, 2024). "PINK1 can have an oncogenic or a tumor suppression function and DJ-1 overexpression has been linked to some neoplasms like melanoma, breast and lung cancers." (PMID 37629650, 2023). "Previous studies have reported a consistency with our own findings, which further demonstrated that a lower expression level of PINK1 was linked to a significantly prolonged overall survival in patients with nonsmall-cell lung cancer (NSCLC) and esophageal squamous cell carcinoma (ESCC)." (PMID 37940999, 2023). "In contrast, a study found that the migraine medicine dihydroergotamine tartrate (DHE) could cause lung cancer cell death via mitophagy and mitochondria-dependent cell apoptosis through the activation of the PINK1/Parkin pathway." (PMID 35326612, 2022). "Indeed, both levels of LETM1 and PINK1 were elevated in the human lung carcinoma implicating for the association of LETM1-mitophagy and lung cancer progression and development." (PMID 35680871, 2022). "Mechanistically, m5C-modified circRREB1 stabilizes the HSPA8 protein by inhibiting its ubiquitination, thereby increasing the expression of PINK1, initiating mitophagy, and ultimately promoting the progression of lung cancer." (PMID 40653497, 2025). "Mechanistically, circRREB1 binds to HSPA8, which in turn increases the expression of PINK1, promotes mitophagy and ultimately promotes the development of lung cancer." (PMID 40653497, 2025). "Mechanistically, circRREB1 directly binds to HSPA8 and stabilizes it by inhibiting ubiquitin-dependent degradation, thereby inducing mitophagy through the HSPA8/PINK1/Parkin signalling axis and ultimately promoting the development of lung cancer." (PMID 40653497, 2025). "We then silenced circRREB1 while overexpressing PINK1 and performed a series of functional assays to explore the ability of circRREB1 to promote lung cancer development through PINK1." (PMID 40653497, 2025). "In NSCLC, the observed PINK1 expression pattern in our study is generally consistent with previous findings in lung cancer research." (PMID 40243539, 2025). "Disruption in the Pink1/Parkin mitophagy pathway, also observed in lung cancer, plays a role in the pathogenesis of chronic obstructive pulmonary disease (COPD)." (PMID 38962310, 2024). "In non–small cell lung cancer, reduction in PINK1 resulted in diminished cell proliferation and reduced cellular ATP production." (PMID 39440945, 2024). "Ginsenoside Rg3 can induce apoptosis of lung cancer cells with the activation of the PINK1-Parkin signaling pathway, suggesting a protective role in mitophagy." (PMID 37686071, 2023). "On the other hand, silencing of PINK1 repressed cell growth and migration and induced apoptosis of lung cancer cells." (PMID 37047483, 2023). "Cell-based analysis has shown that PINK1 inhibition increases apoptosis rate and decreases metastatic abilities across multiple lung cancer cell lines, which is consistent with our results in ovarian cancer cell lines." (PMID 37940999, 2023). "Our previous studies showed that PARK6 (PINK1) can promote migration and proliferation of lung cancer cells by regulating autophagy, and PARK7 (DJ-1) is necessary for the transcription of HIF-1α and survival of colorectal cancer cells." (PMID 34616772, 2021). "Supporting this concept, PINK1 expression has been reported to be upregulated in lung cancer, which promotes the proliferation and chemoresistance." (PMID 33446239, 2021). "Related studies in lung cancer have also shown that the silencing of PINK1 inhibits the migration and invasion of lung cancer cells and that the inhibition of PINK1 enhances the apoptosis rate of cancer cells." (PMID 33981484, 2021).